KLF5 (KLF transcription factor 5)
Diseases named in the same sentence as KLF5 in open-access papers (continued):
Sharing a sentence is not in itself a finding about the gene and the disease.
breast carcinoma (continued). "Among the candidate genes, BAP1 (BRCA1-associated protein 1) drew our special attention because it has been reported to localize in the nucleus and promote breast cancer cell growth similar to KLF5 (refs 31, 32, 33)." (PMID 26419610, 2015). "Here, the authors show that the debuquitinase BAP1 directly stabilizes KLF5, thus promoting basal-like breast cancer cell-cycle progression and metastasis." (PMID 26419610, 2015). "To explore the roles of BAP1 and KLF5 in breast cancer metastasis, we examined breast cancer cell migration and invasion." (PMID 26419610, 2015). "In opposite, the transcript of KLF5 is decreased in various breast cancer cell lines mainly as a consequence of chromosomal deletion or degradation of the KLF5 protein by the proteasome dependent pathway." (PMID 20126619, 2010). "However, KLF5 exhibits a context-dependent role in certain cancer types, notably in breast cancer and prostate cancer." (PMID 41583492, 2025). "Additionally, KLF5 expression is reduced in prostate cancer, leading to the inhibition of angiogenesis, whereas in breast cancer, KLF5 promotes angiogenesis by binding to the promoters of tumor necrosis factor (TNF)α-induced protein 2 (TNFAIP2)." (PMID 40038579, 2025). "Studies have indicated that KLF5 is abnormally expressed in various solid tumors, including breast cancer, prostate cancer, colon cancer, non-small cell lung cancer, and esophageal squamous cell carcinoma, driving the progression and metastasis of these tumors." (PMID 40307891, 2025). "Oncogenic TF KLF5 was correlated with the stemness of breast cancer cells." (PMID 39090713, 2024). "KLF5 is a well-characterized transcription factor involved in breast cancer pathology." (PMID 38468288, 2024). "It has been demonstrated that transcriptional coactivators downstream of the Hippo signaling pathway, including YAP/TAZ, promote the proliferation of breast cancer cells by stabilizing the KLF5 transcription factor, survival, and tumor growth, leading to poor prognosis of breast cancer." (PMID 38571938, 2024). "Furthermore, we measured the expression of FOXO1 and KLF5 in different breast cancer cell lines and found that levels of FOXO1 were comparable to those of KLF5." (PMID 37588224, 2024). "CYTOR could facilitate breast cancer growth and tamoxifen resistance by targeting KLF5 and miR-125a-5p." (PMID 37543427, 2023). "Moreover, BAP1 is a DUB for the transcription factor KLF5 and depletion of BAP1 inhibits breast cancer cell proliferation and tumor growth in vitro and in vivo in an KLF5-dependent manner." (PMID 37543638, 2023). "Moreover, BAP1 was found to stabilize the transcription factor KLF5 and subsequently promoted the breast cancer cell proliferation and tumor growth in vitro and in vivo." (PMID 37543638, 2023). "For example, USP3 facilitates breast cancer cell growth via deubiquitinating KLF5." (PMID 37980532, 2023). "Crosstalk between KLF5 and Hippo factors in breast cancer have been reported." (PMID 37063424, 2023). "We further conducted bioinformatic analysis and biological experiments to investigate whether the top expressed program gene KLF5 could be a potential target for inhibiting breast cancer metastasis." (PMID 36529697, 2023). "Furthermore, we screened Klf5 expression in multiple murine cancer cells, showing that Klf5 was highly expressed in murine breast cancer EMT6 cells and murine colon cancer CT26 cells but expressed at low levels in 67NR cells (murine breast cancer cells)." (PMID 36923542, 2023). "The KLF5-mediated positive feedback loop promotes immune evasion in metastatic breast cancer." (PMID 37744275, 2023).
breast carcinoma (continued). "In fact, HEK293 cells exhibit low basal expression levels of KLF5, which might account for the different effects detected among the breast cancer cell lines and HEK293 cells." (PMID 35779228, 2023). "For instance, BAP1 deubiquitinates and stabilizes the transcription factor KLF5, which is highly expressed in breast cancer and a potent biomarker for unfavorable prognosis in breast cancer patients, and promotes breast cancer cell proliferation, survival, and migration as well as tumor growth." (PMID 36754982, 2023). "In human breast cancer, the oncogenic transcription factor KLF5 (highly expressed in basal-like breast cancer) could be stabilized by BAP1, which further promotes breast cancer cell development both in vitro and in vivo." (PMID 35194152, 2022). "HDAC inhibitors inhibit the expression of KLF5 and the tumorigenesis of breast cancer in vivo." (PMID 36230903, 2022). "Positive feedback loops of LINC00152 and KLF5 promote breast cancer growth and proliferation." (PMID 36033524, 2022). "Breast cancer, cervical cancer, hepatocellular carcinoma, and bladder cancer are all aided by KLF5." (PMID 35345512, 2022). "As expected, these DUBs promote breast cancer development partly via KLF5." (PMID 34575114, 2021). "Apart from enhancing cell proliferation, KLF5 also promotes breast cancer metastasis." (PMID 34575114, 2021). "The deubiquitinase (DUB) BAP1 had been reported to regulate KLF5 stability in breast cancer cells, so we hypothesize that LINC00152 mediates KLF5 depending on the binding of BAP1 and KLF5." (PMID 33842324, 2021). "In addition, the expression of KLF5 in breast cancer correlates with both poorer disease-free survival and overall survival." (PMID 33923166, 2021). "Deubiquitination of KLF5 boosts breast cancer cell proliferation and metastasis." (PMID 34712671, 2021). "Klf5 is highly expressed in breast cancer, possibly indicating that USP3 may play a regulatory role in cancer proliferation." (PMID 34577547, 2021). "Previously published studies reported that LINC00152 could directly inhibit PTEN expression, and KLF5 can directly promote β-catenin expression in breast cancer." (PMID 33842324, 2021). "Moreover, KLF5 knockdown also reduced the enhancement of breast cancer cell tumorigenicity through overexpression of LINC00152." (PMID 33842324, 2021). "Moreover, lncRNA-PVT1 expression is significantly linked to patient survival in those with breast carcinoma, lncRNA-PVT1 has been shown to directly bind and stabilize the KLF5 proteins in breast cancer." (PMID 34475987, 2021). "In addition, BAP1 as a deubiquitinase enhanced cell proliferation and metastasis via deubiquitinating KLF5 in breast cancer cells." (PMID 34226507, 2021). "Besides, KLF5 promotes breast cancer angiogenesis in part through TNF-α-induced protein 2 (TNFAIP2), an angiogenetic factor increasing capillary tube formation, and KLF5 positively regulates TNFAIP2 by directly binding to its promoter." (PMID 33493334, 2021). "Similarly, our study also exhibited a positive feedback loop between LINC00152 and KLF5 in breast cancer." (PMID 33842324, 2021). "KLF5 has been shown to have a tumour promoting function in pancreatic and basal-like breast cancer." (PMID 32880368, 2020). "Besides, knockout of Ataxin-3L inhibits the proliferation of breast cancer cells partly through KLF5." (PMID 32982735, 2020). "All these data suggest that KLF5 could serve as a therapeutic target for different cancers, including breast cancer, colon cancer, prostate cancer and bladder cancer." (PMID 32025209, 2020). "Specifically, KLF5 promotes the migration of bladder cancer cells, breast cancer cells, mouse primary esophageal keratinocytes, bronchial smooth muscle cells and intestinal epithelial cells; in contrast, KLF5 inhibits the migration of HaCaT cells, MCF-10A cells and mouse PDA cells." (PMID 32965165, 2020).
breast carcinoma (continued). "Furthermore, it has been reported that, during breast cancer metastasis, the transcription factor KLF5 recruits p300 and binds to lncRNA RP1 to enhance the activity of the RP1 promoter, and consequently enhances the RP1 expression." (PMID 32929060, 2020). "However, BAP1 has been reported to deubiquitinate KLF5 and to promote breast cancer cell proliferation and metastasis and to play a pro-survival role in cutaneous melanoma." (PMID 30669483, 2019). "Similarly, KLF5 has also been shown to promote breast cancer cell proliferation and survival by upregulating expression of FGF-BP and mPGES1." (PMID 31327760, 2019). "In the TCGA database, higher KLF5 expression correlated with the TN status in breast cancer." (PMID 30206215, 2018). "All these data suggest that KLF5 could serve as a therapeutic target for different cancers, including breast cancer." (PMID 29348684, 2018). "Notably, KLF5 is an essential regulator of hormonal signaling and breast cancer development, and is considered a breast cancer suppressor." (PMID 29914366, 2018). "KLF5 is an important transcription factor for basal-type breast cancer stem cells." (PMID 28480051, 2017). "KLF5 depletion leads to breast cancer cell apoptosis and suppresses xenograft tumor growth in vivo." (PMID 28437471, 2017). "Krüppel-like factor 5 (KLF5) is a transcription factor that is highly expressed in basal-like breast cancers and may serve as a potential therapeutic target for TNBC." (PMID 28030791, 2017). "KLF5 promotes human breast cancer cell proliferation, survival and migration." (PMID 28032601, 2017). "We previously found that KLF5 promotes breast cancer cell survival by stabilizing the MKP1 protein." (PMID 28030791, 2017). "We hypothesize that KLF5 DUBs should stabilize the KLF5 protein and possess oncogenic functions in breast cancer." (PMID 26419610, 2015). "Consistently, these E3 ligases inhibit the expression of KLF5 and cell growth in breast cancer." (PMID 26079537, 2015). "High KLF5 mRNA and protein levels predict unfavorable clinical outcomes for breast cancer patients." (PMID 26079537, 2015). "Our results suggest that BAP1 and KLF5 are potential therapeutic targets for breast cancer." (PMID 26419610, 2015). "Functionally, knockdown of ATXN3L inhibits breast cancer cell proliferation partially through KLF5." (PMID 26079537, 2015). "For KLF5, the smaller fragment of approximately 48 kDa present in the luminal breast cancer cell lines may be attributed to estrogen-dependent processing." (PMID 25789974, 2015). "Our previous studies showed that KLF5 promotes breast cancer cell proliferation, survival and tumor growth, but whether or not TEAD4 has similar functions is not entirely clear." (PMID 25970772, 2015). "Our previous studies demonstrated that KLF5 promoted breast cancer cell proliferation." (PMID 26079537, 2015). "Here we show that, in breast cancer cells, KLF5 is stabilized by the deubiquitinase (DUB) BAP1." (PMID 26419610, 2015). "To further confirm whether ATXN3L knockdown decreases KLF5 protein stability in human breast cancer cells, we knocked down ATXN3L in HCC1806 and SUM1315 (two basal type triple negative breast cancer cell lines), in which KLF5 is highly expressed." (PMID 26079537, 2015). "Since KLF5 DUBs may stabilize the KLF5 protein and promote breast cancer, we screened a siRNA library including 87 human DUBs." (PMID 26079537, 2015). "Although the requirement of YAP and TAZ in maintaining KLF5 protein stability has been reported in breast cancer, whether the same mechanism functions in bladder cancer remains to be proven." (PMID 25170806, 2014). "KLF5 expression is lost in breast cancer specimens, indicating a potential tumor suppressive role." (PMID 23372710, 2013). "Re-expression of KLF5 in breast cancer-derived cells inhibits colony formation." (PMID 20119532, 2009). "On the other hand, KLF5 is a potential tumor suppressor gene in breast cancer." (PMID 20119532, 2009).
breast carcinoma (continued). "Furthermore, Klf5 expression has been suggested as a prognostic factor for overall survival in patients with sporadic breast cancer, with higher Klf5 expression correlating with shorter disease free survival and poorer overall survival." (PMID 20514221, 2009). "However, analysis of tumor and matched normal tissues from TCGA database demonstrated that while elevated KLF5 expression was observed in gastrointestinal tumors, its expression was conversely lower in several other cancers, including breast cancer, prostate cancer, and kidney cancer." (PMID 41583492, 2025). "Notably, KLF5 emerged as a putative substrate with significant links to breast cancer pathology." (PMID 38468288, 2024). "In addition, the existence of the ZEB1/KLF5-mTOR-CCND1/ABCB1 axis may be involved in the paclitaxel response pathway, and it is influencing the susceptibility and prognosis of breast cancer." (PMID 38164285, 2024). "Furthermore, our previous studies demonstrated that BAP1, a novel upstream positive regulator of KLF5 in breast cancer, contributes to ESCC cells proliferation and migration through enhancing KLF5 expression and its downstream genes, including Cyclin D1 and FGF-BP1." (PMID 38087142, 2023). "Moreover, KLF5 is an unfavorable indicator of survival for breast cancer patients." (PMID 36042208, 2022). "Hence, we performed RIP-qPCR analysis to determine whether KLF5 binds to LINC00152 in breast cancer cells." (PMID 33842324, 2021). "Therefore, Ataxin-3L is a novel positive regulator of KLF5 and may serve as potential therapeutic target for breast cancer treatment." (PMID 32982735, 2020). "MIT may suppress breast cancer cell survival by regulating the expression of genes other than KLF5." (PMID 29348684, 2018). "Similarly, LINC00393 achieved significant correlation with the transcription factor krueppel-like factor 5 (KLF5; r = 0.45), whose high expression in basal-like breast cancers was supported by both UBCS (log2FC = 2.18, p = 6.52E-05) and TCGA (log2FC = 1.73, p = 1.07E-30) datasets." (PMID 27685983, 2016). "In addition, reduced KLF5 mRNA levels were demonstrated in breast cancer cell lines." (PMID 26474386, 2015). "Thus, KLF5 expression and/or function in breast cancer remain to be elucidated." (PMID 20119532, 2009). "Previous research showed that YAP1 binds to KLF Transcription Factor 5 (KLF5) dependent on the two WW domains of YAP1 and enhances the growth of breast cancer cells." (PMID 40124511, 2025). "A SE located downstream of the KLF5 gene positively regulated itself in basal-like breast cancers (BLBC), promoting the stem-like characteristics of breast cancer cells." (PMID 39090713, 2024). "In addition, phosphorylation of YBX-1 Ser102 promotes the formation of the YBX-1/KLF5 transcriptional complex, which jointly regulates the expression of keratin 16 and lymphocyte antigen 6 family member D and promotes the proliferation of basal-like breast cancer cells." (PMID 39062595, 2024). "In breast cancer, YBX1 not only initiates KLF5 (Kruppel-Like Factor 5) transcription but also recognizes 5mC-modified KLF5 mRNA to stabilize it, ultimately promoting tumor progression." (PMID 38255791, 2024). "In breast cancer, BAP1 promotes tumorigenesis by stabilizing Kruppel-like factor 5 (KLF5) through deubiquitination, facilitating cell cycle progression, while its depletion inhibits tumorigenesis and lung metastasis." (PMID 39048965, 2024). "Degradation of KLF5 protein can inhibit tumor growth in breast cancer (BC) cells." (PMID 38602556, 2024). "Previous studies demonstrated that miR-21 targets LZTFL1 in breast cancer cells, RASA1 in colon cancer cells, and KLF5 in hepatocellular carcinoma cells." (PMID 37547633, 2023). "Here, KLF5 was proven to be a direct transcription factor for EphA2 in BLBC cells, and its expression was positively correlated in clinical samples from breast cancer patients." (PMID 37063424, 2023).
breast carcinoma (continued). "We previously found that TNFAIP2 was regulated by KLF5 and interacted with the small GTPases RAC1 and CDC42, thereby regulating the actin cytoskeleton and cell morphology in breast cancer cells." (PMID 37787041, 2023). "Transcription factor KLF transcription factor 5 (KLF5) is a member of the BAP1/HCF-1 complex, which is expressed in breast cancer tissues and promotes cancer cell proliferation and metastasis." (PMID 36613989, 2022). "We performed IHC analyses on two breast cancer tissue chips containing a total of 87 patients with TNBC, showing that tumors with high KLF5 protein expression levels were significantly correlated with HDAC1 expression." (PMID 35342356, 2022). "In breast cancer cell lines, BAP1 plays an oncogenic function by directly deubiquitinating and stabilizing KLF5 (Kruppel-like factor 5)." (PMID 36318367, 2022). "Since both KLF5 and ATBF-1 were shown to suppress estrogen signaling in breast cancer cells, Efp is suggested to promote breast cancer by enhancing estrogen receptor signaling." (PMID 35954308, 2022). "Meanwhile, KLF5 directly bound to the promoter of LINC00152 and thus activate its transcription, which ultimately enhances tumorigenesis in breast cancer." (PMID 33842324, 2021). "High expression of KLF5 is observed in ER-/PR-/CK5+ breast cancer cell lines, and is regarded as a poor prognosis factor in breast cancer." (PMID 34575114, 2021). "KLF5-regulated lncRNA RP1 contributed to cell proliferation and metastasis in breast cancer through suppressing p27kip1 translation." (PMID 33931086, 2021). "BAP1 interacts with Krüppel-like factor 5 (KLF5) to stabilize KLF5 and promotes proliferation of breast cancer cells." (PMID 34405018, 2021). "Overexpression of TAZ increased KLF5 and its target FGF-BP expression, while downregulation of TAZ exhibited the opposite effects and retarded growth of 184A1 breast cells and HCC1937 breast cancer cells." (PMID 34226507, 2021). "As a result, KLF5 is stabilized by YAP or TAZ, leading to enhanced proliferation and survival of breast cells or breast cancer cells." (PMID 34712671, 2021). "KLF5 is also able to occupy the lncRNA RP1 promoter to enhance RP1 expression, which plays an oncogenic role in breast cancer." (PMID 32460441, 2020). "KLF5 promotes migration and invasion by upregulating the transcription of TNFAIP2, a tumor necrosis factor-α (TNFα)-induced gene in breast cancer cells." (PMID 33424607, 2020). "Regarding lncRNAs, KLF5 has been reported to regulate LINC0346 in gastric cancer and enhance the expression of RP1 in breast cancer." (PMID 32943987, 2020). "KLF5 has been shown to be regulated by CASC15 and PVT1 in breast cancer along with MALAT1 in pulmonary artery hypertension." (PMID 32943987, 2020). "Dexamethasone was able to decrease sensitivity to cisplatin, as well induce expression of Krüppel-like factor 5 (KLF5), a transcription factor that has been shown to promotes survival and proliferation in basal breast cancers." (PMID 35582576, 2019). "In summary, MIT exhibited strong anti-cancer effects in breast cancer cells, especially TNBC cells, at least partially through down-regulating KLF5 expression." (PMID 29348684, 2018). "Altogether, this study highlights a novel role and signaling pathway for TTK in regulating EMT of TN breast cancer cells through TGF-β and KLF5 signaling, highlighting targetable signaling pathways for TTK inhibitors in aggressive breast cancer." (PMID 30206215, 2018). "We identified ATXN3L as a candidate KLF5 DUB because knockdown of ATXN3L decreased KLF5 protein levels and inhibited breast cancer cell proliferation." (PMID 26079537, 2015).